OOSP3 (oocyte secreted protein family member 3)
Gene: Protein-coding gene on chromosome 11 (59,878,782 to 59,896,483, forward strand). Ensembl gene ENSG00000285231.
Subcellular location: Secreted
Gene Ontology:
Cellular component: extracellular region
Homologues: Orthologues: pig OOSP3 (64% identical).